FBXW2 (F-box and WD repeat domain containing 2)
Description:
Substrate-recognition component of the SCF (SKP1-CUL1-F-box protein)-type E3 ubiquitin ligase complex.
Synonyms: FBW2; FWD2; Md6
Tractability: PROTAC: ubiquitination databases record sites on it.
Gene: Protein-coding gene on chromosome 9 (120,751,978 to 120,793,438, reverse strand). Ensembl gene ENSG00000119402.
Subcellular location (Human Protein Atlas): Nucleoplasm
Pathways (Reactome):
Metabolism of proteins: Association of TriC/CCT with target proteins during biosynthesis; Neddylation
Immune System: Antigen processing: Ubiquitination & Proteasome degradation
Gene Ontology:
Molecular function: protein binding; ubiquitin-protein transferase activity
Biological process: protein modification process; proteolysis; regulation of cell cycle process; SCF-dependent proteasomal ubiquitin-dependent protein catabolic process
Cellular component: cytosol; SCF ubiquitin ligase complex
Genetic constraint (gnomAD): Loss-of-function variants: 11 observed, 43.01 expected, observed/expected ratio (o/e) 0.26, 90% interval 0.16 to 0.42. The upper end of that interval is the gene's LOEUF score, 0.42, which puts it in group 1 of 6, group 1 being the genes least tolerant of losing a copy. Missense variants: 335 observed, 531.58 expected, observed/expected ratio (o/e) 0.63, 90% interval 0.57 to 0.69. Synonymous variants: 187 observed, 209.3 expected, observed/expected ratio (o/e) 0.89, 90% interval 0.79 to 1.01.
Homologues: Orthologues: chimpanzee FBXW2 (100% identical), rabbit FBXW2 (100% identical), macaque FBXW2 (99% identical), guinea pig FBXW2 (99% identical), rat Fbxw2 (99% identical), mouse Fbxw2 (98% identical), tropical clawed frog fbxw2 (89% identical), zebrafish fbxw2 (80% identical), dog FBXW2 (51% identical).
Diseases named in the same sentence as FBXW2 in open-access papers:
FBXW2 is named in the same sentence as 24 diseases in open-access papers, as found by Europe PMC text mining. Sharing a sentence is not in itself a finding about the gene and the disease. The quoted sentences say what the papers report.
lung carcinoma (12 papers, 2017 to 2025). "FBXW2 suppresses proliferation and invasion of lung cancer cells by targeting S phase kinase-associated protein 2 (SKP2) and β-catenin." (PMID 35414786, 2022). "Through TCGA database search, we found numerous FBXW2 mutations in human cancers including lung cancer." (PMID 28090088, 2017). "Ectopic expression of FBXW2 in H23 and H358 lung cancer cells caused a significant reduction in monolayer growth, clonogenic survival and the anchorage-independent growth." (PMID 28090088, 2017). "In lung cancer, FBXW2 ubiquitinates and degrades β-catenin, thereby inhibiting migration and invasion." (PMID 40225854, 2025). "A previous study has shown that β-TrCP1, one of the FBXW proteins (also called FBXW1), can trigger ubiquitination and degradation of FBXW2, thereby maintaining the stability of substrate protein and accelerating the growth of lung cancer cells." (PMID 40721413, 2025). "For instance, FBXW2 induced ubiquitin-mediated proteolysis of β-catenin to delay invasive and migratory activities of lung cancer cells." (PMID 40721413, 2025). "On the other hand, FBXW2 also has been confirmed to inhibit the tumor growth and metastasis of lung cancer by promoting ubiquitylation and degradation of β-catenin and S phase kinase-associated protein 2 (SKP2)." (PMID 35499593, 2022). "Here, consistent with our previous study in lung cancer, we found that FBXW2 was a tumor suppressor in PCa by inhibiting the cell growth and metastasis." (PMID 35499593, 2022). "FBXW2, acts as a tumor suppressor gene in lung cancer by directly degrading substrates or by regulating other E3 ligases." (PMID 35499593, 2022). "Our recent study showed that FBXW2 was a tumor suppressor in lung cancer by promoting the ubiquitylation of SKP2 and β-catenin." (PMID 35499593, 2022). "FBXW2 is a poorly characterized F-box protein, as a tumor suppressor that inhibits growth and metastasis of lung cancer by promoting ubiquitylation and degradation of oncogenic proteins, including SKP2 and β-catenin." (PMID 35499593, 2022). "Sun’s group reported that FBXW2 suppressed lung cancer cell migration and invasion by inhibiting the escape of the cells, and in their working model, FBXW2 was expressed in the cytoplasm." (PMID 34736516, 2021). "Yang found that FBXW2 can participate in the occurrence and development of lung cancer by regulating epidermal growth factor-AKT1, β-catenin." (PMID 33029266, 2020). "To pursue additional involving genes, we recently reported that FBXW2 (F-box and WD-repeat domain-containing 2), a poorly characterized F-box protein, acts as a tumor suppressor to inhibit growth and survival of lung cancer cells." (PMID 30918250, 2019). "Here, the authors show that FBXW2 suppresses lung cancer migration and invasion by promoting degradation of β-catenin and this is dependent on EGF-AKT1." (PMID 30918250, 2019). "Upon FBXW2 knockdown, accumulated β-cateninpS552 enters the nucleus to transactivate expression of MMPs to promote migration, invasion and metastasis of lung cancer cells." (PMID 30918250, 2019). "We first observed in general an inversely correlated expression pattern between FBXW2 and phosphorylated β-catenin-Ser552 as well as total β-catenin in multiple lung cancer cell lines." (PMID 30918250, 2019). "We have recently characterized FBXW2, a poorly characterized F-box protein, as a tumor suppressor that inhibited growth and survival of lung cancer cells by promoting ubiquitylation and degradation of oncogenic protein SKP24." (PMID 30918250, 2019). "Collectively, our study demonstrates that FBXW2 inhibits tumor migration, invasion and metastasis in lung cancer cells by targeting β-catenin for degradation." (PMID 30918250, 2019). "We transfected FBXW2 or β-catenin alone, or in combination into lung cancer cells and found that ectopic expression of FBXW2 suppressed cell migration and invasion, which can be blocked by simultaneous transfection of β-catenin." (PMID 30918250, 2019).
lung carcinoma (continued). "FBXW2 has tumour suppressor activity against lung cancer cells and blocks oncogenic function of both β-TrCP1 and SKP2." (PMID 28090088, 2017). "Here we showed that FBXW2 acts as a novel tumour suppressor in lung cancer with following lines of supporting evidence." (PMID 28090088, 2017). "We found that in contrast to oncogenic β-TrCP1 and SKP2, FBXW2 acts as a tumour suppressor to inhibit growth and survival of lung cancer cells, and high FBXW2 expression predicts a better patient survival." (PMID 28090088, 2017). "Collectively, these results strongly suggest that FBXW2 has tumour suppressor activity against lung cancer, which is likely mediated by accumulation of few tumour suppressor proteins." (PMID 28090088, 2017). "We, therefore, added serum to serum-starved cells and found that ectopically expressed β-TrCP1 significantly shortened the protein half-life of exogenous FBXW2 in H1299 or H358 lung cancer cells." (PMID 28090088, 2017). "However, emerging evidences characterized FBXW2 as a tumor suppressor that inhibited survival and growth of lung cancer cells, it is concerning the fragment would antagonize this positive effect of FBXW2 on tumor." (PMID 33101872, 2020). "Thus, FBXW2 suppresses migration, invasion, and metastasis of lung cancer cells via promoting ubiquitylation and degradation of β-catenin." (PMID 30918250, 2019). "FBXW2 inhibits proliferation of lung cancer cells by targeting SKP2 for degradation." (PMID 30918250, 2019). "Indeed, while FBXW2 knockdown increased the levels of total β-catenin as well as phosphorylated β-catenin-Ser552, FBXW2 overexpression reduced them in a dose-dependent manner in various lung cancer cell lines." (PMID 30918250, 2019). "Taken together, by targeting β-catenin, FBXW2 acts as an inhibitory protein against migration, invasion and metastasis of lung cancer cells in both in vitro cell culture and in vivo mouse models, although the tail-vein injection of tumor cells is not a spontaneous metastasis model." (PMID 30918250, 2019). "Our recent study identified FBXW2 as a tumor suppressor via promoting ubiquitylation of SKP2 (S phase kinase-associated protein 2) for targeted degradation to inhibit growth and survival of lung cancer cells." (PMID 30918250, 2019). "Taken together, these results demonstrate that FBXW2 inhibition of migration and invasion in lung cancer cells is mediated via promoting β-catenin degradation and consequent downregulation of MMP expression, which is preferentially regulated by the β-catenin-S552D-TCF4M/S transcription factors." (PMID 30918250, 2019). "To determine the biological significance of FBXW2-mediated β-catenin degradation, we measured effect of FBXW2 on migration and invasion of lung cancer cells, since it was reported that phosphorylation of β-catenin by AKT1 increased its transcriptional activity and promoted cancer cell invasion." (PMID 30918250, 2019). "We next determined the biological function of FBXW2 against lung cancer cells." (PMID 28090088, 2017). "To elucidate the mechanism by which FBXW2 suppressed proliferation and survival of lung cancer cells, we measured, after manipulation of FBXW2, the levels of few tumour suppressive and oncogenic proteins, known to regulate cell growth as well as known to be substrates of F-box proteins." (PMID 28090088, 2017). "However, whether FBXW2 targets other substrates to regulate the migration and invasion of lung cancer cells is totally unknown." (PMID 30918250, 2019). "By defining FBXW2 as a substrate of β-TrCP1 and an E3 for SKP2, we established, for the first time, a signalling cascade of three F-box proteins β-TrCP-FBXW2-SKP2 in lung cancer cells." (PMID 28090088, 2017). "Based upon the biological functions of β-TrCP1, FBXW2 and SKP2 characterized in this study, we proposed an oncogene-tumour suppressor-oncogene axis in lung cancer cells." (PMID 28090088, 2017).
lung carcinoma (continued). "FBXW2 has been confirmed to promote ubiquitylation and degradation of oncogenic proteins, such as SKP2 and β-catenin, resulting in suppression of tumor growth and metastasis of lung cancer." (PMID 35499593, 2022). "Functionally, FBXW2 overexpression inhibits migration and invasion by blocking transactivation of MMPs driven by β-catenin, whereas FXBW2 knockdown promotes migration, invasion and metastasis both in vitro and in vivo lung cancer models." (PMID 30918250, 2019). "We transfected β-TrCP1, FBXW2 (wt versus mutant) and SKP2 alone or in various combinations into lung cancer cells and found that transfection of β-TrCP1 alone stimulated the monolayer growth and increased clonogenic survival of lung cancer cells." (PMID 28090088, 2017). "Finally, we performed an siRNA-based knockdown experiment in A549 and H23 lung cancer cells, and found endogenous levels of FBXW2 protein, but not FBXW2 mRNA were increased upon β-TrCP1 knockdown." (PMID 28090088, 2017).
breast carcinoma (6 papers, 2020 to 2025). "Our in vitro and in vivo studies reveal that FBXW2 prevents breast cancer progression by promoting Lys-48-linked polyubiquitination to direct proteasomal degradation of Moesin through the canonical SCF complex." (PMID 37736741, 2023). "To further validate this regulatory axis in breast cancer, we assessed the correlation among the expression levels of these four proteins (FBXW2, pAKT, Moesin and SKP2) in HR positive breast cancer patients." (PMID 37736741, 2023). "Collectively, FBXW2 suppresses breast cancer progression both in vitro and in vivo by negatively regulating Moesin." (PMID 37736741, 2023). "Overall, our study established tumor suppressor FBXW2 as a bonafide E3 ligase for Moesin in breast cancer." (PMID 37736741, 2023). "Recently, it was shown that FBXW2 suppresses breast cancer growth through controlling NF-κB p65 level." (PMID 37736741, 2023). "Taken together, FBXW2 directly interacts with Moesin and shows an inverse correlation with Moesin’s expression in breast cancer cell lines and patient samples." (PMID 37736741, 2023). "Further, FBXW2 is under expressed whereas Moesin is highly upregulated in breast cancer cell lines and patient samples and their converse correlation is closely associated with poor patient prognosis." (PMID 37736741, 2023). "In this study, we show that F-box and WD repeat-containing protein 2 (FBXW2) functions as a tumor suppressor in breast cancer." (PMID 37736741, 2023). "We showed that FBXW2 acts as a negative regulator of Moesin at the posttranslational level and it is under expressed in breast cancer cell lines and patient samples." (PMID 37736741, 2023). "Taken together, these observations suggest that FBXW2 prevents breast cancer progression, at least partly, by negatively regulating SKP2 levels." (PMID 37736741, 2023). "The ubiquitination of p65 (RELA) and its degradation by E3 ligase, FBXW2, leads to suppressed breast cancer stemness and tumorigenesis." (PMID 38201482, 2023). "Further, we observed a good converse correlation in the expression levels of Moesin and FBXW2 among the cell lines and breast cancer patients." (PMID 37736741, 2023). "We showed that FBXW2 suppresses breast cancer progression through directing proteasomal degradation of Moesin." (PMID 37736741, 2023). "We also identified an oncogenic AKT-Moesin-SKP2 axis which promotes breast cancer progression and FBXW2 restricts this axis to prevent cancer progression." (PMID 37736741, 2023). "Taken together, these results show that FBXW2 controls the proliferation of breast cancer cells through controlling Moesin expression." (PMID 37736741, 2023). "Further, we examined the role of FBXW2 on breast cancer malignancy by monitoring anchorage-independent growth, migration, and invasion of MCF7 cells." (PMID 37736741, 2023). "Next, we examined the expression levels of FBXW2 and Moesin in normal breast epithelial cell line and different subtypes of breast cancer cell lines (luminal, human epidermal growth factor receptor 2 positive (HER2+), and triple negative breast cancer (TNBC))." (PMID 37736741, 2023). "So, these results showed that FBXW2 inhibits malignancy of breast cancer cells in vitro by negatively regulating Moesin." (PMID 37736741, 2023). "Collectively, our study reveals that FBXW2 functions as a tumor suppressor in breast cancer by restricting AKT-Moesin-SKP2 axis." (PMID 37736741, 2023). "For example, TRIM47, TRIM27, UBR5, and FBXW2 can regulate breast cancer progression and endocrine therapy sensitivities via the polyubiquitination of PKC‐ε, P21, β‐catenin, and MSX2, respectively." (PMID 35843886, 2022). "In contrast, FBXW2 is under expressed in all the breast cancer cell lines tested compared to the normal cell line indicating that ablation of FBXW2 might be responsible for accumulation of Moesin in breast cancer cells." (PMID 37736741, 2023). "Hence, there exists an AKT-Moesin-SKP2 oncogenic axis in breast cancer, which is counteracted by FBXW2." (PMID 37736741, 2023).
breast carcinoma (continued). "Since Moesin is a well-established oncogene and FBXW2 is a putative tumor suppressor, we sought to determine whether FBXW2 regulates breast cancer progression through controlling the expression level of Moesin." (PMID 37736741, 2023). "We found that breast cancer patients with high FBXW2/low Moesin levels have significantly better RFS compared to those with low FBXW2/high Moesin, suggesting that the expression levels of both FBXW2 and Moesin could be used as prognostic biomarkers in breast cancer." (PMID 37736741, 2023). "We speculated that FBXW2 may regulate several oncogenes to suppress breast cancer progression." (PMID 37736741, 2023). "Hence, FBXW2 was immunoprecipitated from MCF7 breast cancer cells." (PMID 37736741, 2023). "Trypan blue cell count assay revealed that depletion of FBXW2 results in significant increased cell proliferation compared to the wild-type (NS) MCF7 and 4T1 (murine breast cancer cell line) cells (expressing scramble shRNA)." (PMID 37736741, 2023). "Biologically, FBXW2 promotes tumor sphere formation by upreglating SOX2 via inducing MSX2 degradation, while MLN4924 sensitizes breast cancer cells to tamoxifen by depleting SOX2 via targeting the FBXW2-MSX2 axis." (PMID 31748974, 2020).
prostate carcinoma (5 papers, 2020 to 2025). A carcinoma that arises from epithelial cells of the prostate gland. "FBXW2 is considered a powerful therapeutic target for many other solid tumors, such as lung, breast, and prostate cancers, most of which display frequent KRAS mutations." (PMID 40721413, 2025). "In prostate cancer, FBXW2 reduced epidermal growth factor receptor (EGFR) protein stability, thus suppressing cell proliferation and metastatic ability." (PMID 40721413, 2025). "In prostate cancer, FBXW2 facilitates epidermal growth factor receptor ubiquitination and degradation, thereby inhibiting EGF-induced growth and metastasis." (PMID 40225854, 2025). "Intriguingly, FBXW2 was an E3 ligase for EGFR in prostate cancer." (PMID 35499593, 2022). "Thus, our data uncover a novel that FBXW2 as a tumor suppressor of prostate cancer, inhibits EGFR downstream by promoting EGFR ubiquitination and degradation, resulting in repression of cell proliferation and metastasis." (PMID 35499593, 2022). "However, what the biological functions of FBXW2 in prostate cancer cells and whether FBXW2 targets other substrates to involve in progression of prostate cancer is still unclear." (PMID 35499593, 2022).